CCL2 (C-C motif chemokine ligand 2)
Diseases named in the same sentence as CCL2 in open-access papers (continued):
Sharing a sentence is not in itself a finding about the gene and the disease.
Insulin resistance (613 papers, 2006 to 2026). Increased resistance towards insulin, that is, diminished effectiveness of insulin in reducing blood glucose levels. "IL-1β induces the production of a wide range of cytokines and chemokines implicated in insulin resistance and type 2 diabetes such as CC-chemokine ligand 2 (CCL2), CCL3, and CXC-chemokine ligand 8 (CXCL8)." (PMID 39606781, 2024). "We previously showed that serum levels of C-C motif chemokine ligand 2 the major chemokine released by monocytes and macrophages and associated with insulin resistance, were higher in testosterone-treated KS patients than in healthy controls." (PMID 37148417, 2023). "This SNP was further shown to be associated with higher CCL2 levels in patients with insulin resistance compared to those with insulin sensitivity." (PMID 33540898, 2021). "Similar to the in vitro results, knocking out adipocyte mTORC2/Rictor led to the loss of FGF1 function in controlling Ccl2 expression and ameliorating insulin resistance." (PMID 32979037, 2020). "Pro-inflammatory cytokines like IL-1β induces apoptosis in insulin-producing β-cells while CCL2 and TNFα are known to impair insulin signalling, and therefore causing insulin resistance." (PMID 27030821, 2015). "Increased expression of CCL2 can induce insulin resistance, which is usually associated with hyperinsulinemia and increased glucose uptake by cancer cells." (PMID 26174804, 2015). "Accordingly CCR2, the receptor of CCL2, deficient mice show attenuated macrophage infiltration, inflammation, and insulin resistance." (PMID 23781214, 2013). "CCL2, also known as monocyte chemoattractant protein-1 (MCP-1), is a chemokine associated with cerebral ischemia and rheumatoid arthritis, insulin resistance and prostate cancer." (PMID 21980379, 2011). "Inflammatory cytokines such as TNF-γ and IL-6 as well as the chemokine CCL2, produced by proinflammatory M1-like AT macrophages and hypertrophic adipocytes inhibit local insulin signalling pathways to cause adipose and systemic insulin resistance." (PMID 37642146, 2023). "Furthermore, TMAO causes inflammation in adipose tissue, inducing insulin resistance by increasing the serum inflammatory cytokine C-C motif chemokine 2 (CCL2) level." (PMID 34685614, 2021). "OPN, IL‐6 and CCL‐2 have all been implicated in insulin resistance." (PMID 27135421, 2016). "Conversely, when IKK2 is superactivated in fasting liver or neonatal liver, where IKK1 is low and FOXO1 activity is high, FOXO1 synergizes with p65/p50 to cause insulin resistance and induce proinflammatory IL-1β, IL-6, CCL2, and CCL20, resulting in progressive inflammation and/or liver fibrosis." (PMID 26219821, 2015). "In addition to acting as a chemokine, CCL2 has also been shown to directly cause insulin resistance." (PMID 24843075, 2014). "While levels of CCL2 did not correlate with insulin sensitivity in this study, it is known that CCL2 does cause insulin resistance when mice are infused directly with this chemokine, and there is some evidence that this is also the case in adult humans although the evidence is not conclusive." (PMID 23557387, 2013). "Additionally, experimental studies have shown that CCR2 and CCL2-deficient mice exhibited attenuated inflammation in adipose tissue, decreased adipose tissue macrophages, and protection against high fat diet-induced insulin resistance." (PMID 33042108, 2020). "Whilst PA induced insulin resistance, OA protected against it, also reducing the release of MCP-1/CCL2 and augmenting eNOS biosynthesis." (PMID 41465574, 2025). "The inhibition of CCL2 in animal models has been reported to modulate the inflammation cascade and ameliorate the symptoms of insulin resistance." (PMID 39063997, 2024). "Intermittent hypoxemia during sleep increases selenoprotein P, which is one of the hepatokines, as well as TNF-α, CCL-2, and resistin, members of adipokines, to induce insulin resistance via direct cellular mechanisms." (PMID 38893645, 2024).
Insulin resistance (continued). "The serum concentration of CCL2 correlates with insulin resistance and a high body–mass index (BMI)." (PMID 36983642, 2023). "Transgenic expression of CCL2 in adipose tissue increases macrophage infiltration, inflammation, and insulin resistance, whereas knockdown of CCL2 or CCR2 impairs the migration of macrophages into adipose tissue." (PMID 37457301, 2023). "Several studies have shown that elevated levels of CCL2, CCL3 and CCL11 are associated with insulin resistance contributing to the development of T2DM33." (PMID 38092892, 2023). "Here we demonstrated that the injection of nondiabetic plasma-treated SVFs into the adipose tissue of Leprdb/db mice decreased proinflammatory cytokine expression, suppressed plasma DPP4 activity and CCL2 levels, and ameliorated insulin resistance." (PMID 35883204, 2022). "M1 ATMs form the “crown like” structure around dead adipocytes and produce TNF-α, IL-6, and CCL2, accelerating chronic inflammation and insulin resistance." (PMID 35885044, 2022). "Reactive oxygen species (ROS) production and the secretion of inflammatory cytokines like TNFα and C-C motif chemokine ligand 2 are elevated under conditions of excess nutrition, which eventually impairs insulin signaling and results in insulin resistance." (PMID 36207302, 2022). "The chemokine CCL2 is produced in adipose tissue and triggers the development of insulin resistance and steatosis, two of the major characteristics present in the HFD-fed Apoe−/− mice, in which its expression was significantly increased." (PMID 34850865, 2021). "Attenuation of TNFα/IL-1β/CCL2-mediated inflammation in metabolic organs has been shown to improve insulin resistance, consistent with the observed reduction of fasting insulin and HOMA-IR in KrO-treated mice." (PMID 34444996, 2021). "Based on these findings, we suggested that the metabolic effects of FGF1 on adipose tissue inflammation and systemic insulin resistance occurred by inhibiting the transcription and expression of Ccl2 in eWAT." (PMID 32979037, 2020). "Given that macrophage infiltration and insulin resistance in adipose tissues is mainly mediated by the CCL2/CCR2 chemotaxis system, we further conducted immunofluorescence and Western blot analysis to examine CCL2 protein levels in epididymal adipose tissue." (PMID 32979037, 2020). "This subsequently inhibited the expression of Ccl2 in adipose tissue, thereby ameliorating systemic insulin resistance." (PMID 32979037, 2020). "In support of this argument, TNF-α, IL-6, IL-8, CCL2, CCL4, CCL5, and CCL19 were found to be implicated with metabolic inflammation or insulin resistance in various tissues and organs." (PMID 31718015, 2019). "MiR-126 negatively regulates the expression of the CCL2 gene, which is involved in the development of the obesity-induced inflammation and insulin resistance in the skeletal muscle." (PMID 30445764, 2018). "Chemokine C-C motif-ligand 2 (CCL2) is a pro-inflammatory cytokine involved in the development of insulin resistance and macrophage infiltration and recent evidence supports a role of CCL2 in diabetic nephropathy." (PMID 30090066, 2018). "MiR-126 regulates the expression of the chemokine (C-C motif) ligand 2 (CCL2), which has been associated with the recruitment of inflammatory cells and insulin resistance." (PMID 30445764, 2018). "CCL2 plays a crucial role in the recruitment of macrophages into WAT and upregulation of TNF-α, IL-6 and CCL2 in WAT is critically involved in the induction of systemic insulin resistance." (PMID 26871288, 2016). "As a final remark we can conclude that an increase of CCL2 serum levels is associated with the polymorphic phenotypes (A+/Ile+) of the polymorphisms G-2518A in CCL2 and Val64Ile in CCR2 in individuals with insulin resistance of Mexican population." (PMID 26839895, 2016).
Insulin resistance (continued). "Blockade of CCR2, a chemokine receptor for ligands CCL2, 7, 8, 13, and 162, has been reported to improve insulin resistance, lipid metabolism, and diabetic nephropathy in type 2 diabetic mice." (PMID 26648169, 2015). "Especially, MCP-1/CCL2 recruits macrophages into this compartment contributing to insulin resistance." (PMID 25309544, 2014). "Our results are in agreement with another recent study that showed CCL2 levels were elevated in obese compared to lean children, and in that study CCL2 levels correlated with insulin resistance." (PMID 23557387, 2013). "Actually, CCL2 modifies lipid and glucose metabolism and contributes to insulin resistance and hepatic steatosis." (PMID 24453432, 2013). "It is quite important to follow our patients to see if they develop insulin resistance and how CCL2 levels correlate with this." (PMID 23557387, 2013). "The monocyte chemoattractant protein-1 (Mcp1, also known as chemokine (C-C motif) ligand-2, Ccl2), a marker of M1 macrophages, increases macrophage infiltration, inflammation and insulin resistance in transgenic mice." (PMID 23620818, 2013). "Accordingly, HFD fed SFRP5 deficient mice Sfrp−/− have insulin resistance and fatty liver along with enhanced inflammatory macrophage accumulation to produce IL-6, TNF-α, and CCL2 suggesting that SFRP5 is an anti-inflammatory adipokine." (PMID 23781214, 2013). "Transgenic expression of MCP-1 also known as chemokine ligand 2 (Ccl2), in adipose tissue increases macrophage infiltration, inflammation, and insulin resistance." (PMID 22891067, 2012). "Additionally, multivariable linear regression identified irisin as the only independent predictor of insulin resistance, while CCL2 was the strongest predictor of BMI." (PMID 42196825, 2026). "Thus, the increased secretion of TNF, IL1B, and CCL2 in the hepatic macrophages of old mice potentially aggravates insulin resistance, liver steatosis, and the progression of chronic liver diseases." (PMID 37602516, 2023). "Levels of CCL2 were increased in livers of NASH patients and murine models of NASH and fibrosis, and infiltration of Ly6Chigh CCR2+ macrophages is considered a critical pathogenic event promoting the progression to steatohepatitis and insulin resistance." (PMID 35955975, 2022). "Hence, the authors summarized that hypoxia downregulates miR-452 which in turn increases the expression of CCL2, RETN, and TNFα, causing insulin resistance." (PMID 33540898, 2021). "The inhibition of M1 expression in the adipose tissue represses JNK activation, plasma DPP4 activity and CCL2 levels, as well as liver inflammatory cytokines expression that may ultimately attenuate insulin resistance and glucose intolerance in diabetes." (PMID 34043673, 2021). "Higher Ccl2 levels recruit pro-inflammatory macrophages, resulting in increased gut permeability, activation of the inflammasome, and finally in inflammation and AT insulin resistance." (PMID 33540898, 2021). "Similarly, mice in which Ccl2 had been deleted showed resistance to high fat diet-induced insulin resistance and hepatic steatosis, an effect that was accompanied by reduced expression of TNFα in adipose tissue." (PMID 32158768, 2020). "The circulating level of CCL2 is correlated with insulin resistance and T2D." (PMID 33207809, 2020). "From our results, the expression of TNFα and CCL2 was increased in adipocytes and TNFα and CCL2 could act as adipokines contributing to worsening insulin resistance in the IH condition." (PMID 31013606, 2019). "Ccl2, also referred to as monocyte chemoattractant protein-1, is a key regulator of monocyte infiltration of adipose tissue that plays a central role in the development and maintenance of chronic adipose tissue inflammation and insulin resistance." (PMID 31013606, 2019).
Insulin resistance (continued). "CCL2, also referred as monocyte chemoattractant protein-1, is a key regulator of monocyte infiltration in adipose tissue and plays a central role in the development and maintenance of chronic adipose tissue inflammation and insulin resistance." (PMID 31557884, 2019). "CCL2, also referred as monocyte chemoattractant protein-1, is a key regulator of monocyte infiltration of adipose tissue, and it plays a central role in the development and maintenance of chronic adipose tissue inflammation and insulin resistance." (PMID 31683992, 2019). "Ccl2 encodes for MCP-1, a pro-inflammatory chemokine that is suggested to stimulate the recruitment of macrophages and dendritic cells, and to further increase the expression of cytokines that exacerbate inflammation-induced insulin resistance." (PMID 29847581, 2018). "Inhibition of proinflammatory cytokines and chemokines, such as TNF-α, IL-1β, IL-6, and CCL2, may reduce adipose tissue inflammation and insulin resistance." (PMID 29507865, 2018). "In a large cohort of Caucasians, circulating CCL2/MCP-1 was increased in type 2 diabetes subjects and presence of the MCP-1 G-2518 allele was associated with decreased plasma CCL2/MCP-1 levels as well as prevalence of insulin resistance and type 2 diabetes." (PMID 24733068, 2014). "While CCL2 has been implicated in inflammation and insulin resistance, its correlation with fitness has not been studied previously." (PMID 23557387, 2013). "Moreover, studies in transgenic mice that over-express ccl2 under the control of the adipose tissue-specific AP2 promoter indicate that CCL2 in adipose tissue, per se, induces macrophage recruitment and insulin resistance." (PMID 20936118, 2010). "The CCL2/CCR2 axis is a major component of insulin resistance in obese mice." (PMID 20936118, 2010). "Moreover, mice overexpressing Ccl2 specifically in adipose tissue exhibit insulin resistance and increased hepatic triglyceride content." (PMID 19513120, 2009). "According to a previous study, the alleviation of insulin resistance (hyperglycemia and hyperinsulinemia) by dietary cholest-5-en-3-one is attributable to a decrease in the production of inflammatory cytokines, such as Ccl2 (MCP-1) and Il6 (IL-6), in the adipose tissues." (PMID 38921456, 2024). "In addition, dual CCR2/CCR5 antagonism could ameliorate insulin resistance and inflammation in high-fat diet-fed mice and decrease CCL2/CCL4‐induced migration of macrophage." (PMID 33968046, 2021). "CCL2 has been shown to play a unique role among several cytokines that may influence the function of adipocytes, recruitment of AT macrophages, and the link between AT inflammation and insulin resistance." (PMID 33540898, 2021). "It is believed that CCL2 may contribute to the development of insulin resistance (IR)." (PMID 34768469, 2021). "Therefore, we treated adipocytes with TNF-α, which dramatically increased the expression of genes involved in insulin resistance in adipocytes, such as IL-6, CCL2, and chemokine ligand 9 (CCL9), but significantly reduced glucose transporter 4 (GLUT4) expression." (PMID 32024237, 2020). "Adding to Ccl2 and Tnfα, Retn may be one of the adipokines increasing insulin resistance in IH." (PMID 31013606, 2019). "Thus, inflamed adipose tissue could promote low-grade systemic inflammation by releasing proinflammatory cytokines and chemokines (IL-1ß, TNF-α, IL-6, leptin, CCL2, CCL3, and CXCL8) and causing insulin resistance and endothelial dysfunction." (PMID 28512338, 2017).
Insulin resistance (continued). "For example, monocyte-chemo attractant protein-1 (Mcp-1, also referred to as Chemokine (C-C motif) ligand 2, Ccl-2) and its receptor, chemokine-receptor-2 (Ccr-2), have both been reported to modulate infiltration of macrophages into adipose tissue, thereby contributing to insulin resistance." (PMID 19305508, 2009). "When adipose tissue recruits macrophages due to the overexpression of MCP1, which is a chemokine ligand known as CCL2, liver insulin resistance is observed with increased TNF-α expression in adipose tissue." (PMID 40362446, 2025). "CCl2 critically supports macrophage recruitment to WAT, leading to local tissue inflammation and ultimately glucose intolerance and insulin resistance." (PMID 38652276, 2024). "Activated Kupffer cells secrete TNF to amplify the effects of insulin resistance and activate the nuclear factor-κB (NFKB) and C-C motif chemokine ligand 2 (CCL2)." (PMID 35052690, 2021). "The present study aims to investigate the levels of leptin, resistin, visfatin, SFRP5, MCP-1/CCL2, and RBP4 as well as their correlations with insulin resistance and clinical parameters of overweight and T2DM in a Vietnamese study group." (PMID 29785210, 2018). "One of the molecular mechanisms by which insulin resistance contributes to the development of MASLD and its progression to MASH is the release of molecules that perpetuate low-grade inflammation, such as IL-6, CCL2/MCP-1, and CCL19." (PMID 39859069, 2025). "Thus, it is not surprising that key proinflammatory cytokines, including TNF-a, IL-6, CCL2, and CCL5, which are present at high serum concentrations in patients with insulin resistance, are mediators of HSC activation." (PMID 37735474, 2023). "The chemokine ligand 2 (CCL2)–CC chemokine receptor type 2 (CCR2) axis plays a critical role in the egress of Ly6C+ inflammatory monocytes from the bone marrow (BM) to the gut mucosa and is involved in insulin resistance." (PMID 34444972, 2021). "In MCP-1 or CCR2 knockout mice, there is a decrease in macrophage infiltration in adipose tissue whereas overexpressing CCL2 enhances macrophage accumulation and insulin resistance." (PMID 23637889, 2013). "Finally, injection of non-diabetic plasma decreased plasma DPP4 activity and CCL2 levels, and ameliorated insulin resistance." (PMID 34043673, 2021). "The over-expression of CCL2 in adipose tissue increases macrophage recruitment, whereas a reduction of CCL2 or its receptor CCR2 lowered proinflammatory macrophages accumulation in the adipose tissue and provides protection from insulin resistance as well as hepatic steatosis." (PMID 32708964, 2020). "Several groups have reported that mice with targeted deletions in the genes for MCP-1/CCL2 and its receptor CCR2 have reduced adipose tissue macrophage (ATM) content, decreased inflammation in fat and protection from high-fat (HF) diet-induced insulin resistance." (PMID 29694633, 2018). "However, it is known that the binding of chemokines such as monocyte chemoattractant protein 1 (MCP-1), also known as C-C motif ligand (CCL) 2, with its receptor induces recruitment of macrophages in adipocyte and hepatocyte, leading to liver steatosis and insulin resistance in obese patients." (PMID 34522493, 2021). "A recent in vitro study found that the expressions of resistin (RETN), TNF-α, and C-C motif chemokine ligand 2 (CCL2) of mouse and human pre-adipocytes/adipocytes, were increased by IHR via down-regulation of miR-452, which may play a protective role in the development of insulin resistance." (PMID 31208080, 2019). "However the role CCL2 in inflammation and insulin resistance is not clear." (PMID 23781214, 2013). "Taken together, their results indicate that an increase in the concentration of CCL2 in the circulation is sufficient to induce systemic insulin resistance irrespective of adipose tissue inflammation and suggest that CCL2 may be a direct effector in regulating metabolism." (PMID 20936118, 2010).
Insulin resistance (continued). "Mice lacking monocyte chemoattractant protein-1 (Mcp1/Ccl2) or its receptor, CC motif chemokine receptor-2 (CCR-2), have decreased macrophage accumulation in adipose tissue and inflammation in fat and attenuated insulin resistance during a high fat diet." (PMID 23626755, 2013).